CPB2 (carboxypeptidase B2)
Description:
Cleaves C-terminal arginine or lysine residues from biologically active peptides such as kinins or anaphylatoxins in the circulation thereby regulating their activities. Down-regulates fibrinolysis by removing C-terminal lysine residues from fibrin that has already been partially degraded by plasmin.
Synonyms: CPU; pCPB; TAFI
Tractability: Small molecule: a structure with a bound ligand is known; a high-quality ligand is known; it belongs to a druggable protein family. Antibody: its Gene Ontology location is reachable by antibodies, with high confidence; UniProt places it where antibodies can reach, with medium confidence; UniProt predicts a signal peptide or a membrane-spanning region. PROTAC: a small molecule that binds it is known.
Target class: Metallo protease; Metallo protease MC clan; Protease; Metallo protease M14A subfamily; Enzyme
Gene: Protein-coding gene on chromosome 13 (46,052,958 to 46,105,073, reverse strand). Ensembl gene ENSG00000080618.
Subcellular location: Secreted
Pathways (Reactome):
Immune System: Regulation of Complement cascade
Metabolism of proteins: Metabolism of Angiotensinogen to Angiotensins
Gene Ontology:
Molecular function: metallocarboxypeptidase activity; carboxypeptidase activity; zinc ion binding
Biological process: fibrinolysis; proteolysis
Cellular component: extracellular exosome; extracellular region
Genetic constraint (gnomAD): Loss-of-function variants: 28 observed, 27.96 expected, observed/expected ratio (o/e) 1, 90% interval 0.74 to 1.37. The upper end of that interval is the gene's LOEUF score, 1.37, which puts it in group 5 of 6, group 1 being the genes least tolerant of losing a copy. Missense variants: 234 observed, 292.74 expected, observed/expected ratio (o/e) 0.8, 90% interval 0.72 to 0.89. Synonymous variants: 104 observed, 105.25 expected, observed/expected ratio (o/e) 0.99, 90% interval 0.84 to 1.16.
Homologues: Orthologues: chimpanzee CPB2 (99% identical), pig CPB2 (85% identical), mouse Cpb2 (84% identical), guinea pig CPB2 (83% identical), rabbit CPB2 (83% identical), rat Cpb2 (81% identical), dog CPB2 (80% identical), tropical clawed frog cpb2 (57% identical), zebrafish cpb2 (47% identical), Caenorhabditis elegans T06A4.1 (36% identical), Caenorhabditis elegans Y47G6A.19 (34% identical), Drosophila melanogaster CG3097 (31% identical), and 18 more. Paralogues in human: CPB1 (40% identical), CPA3 (39% identical), CPA6 (38% identical), CPA2 (37% identical), CPA5 (37% identical), CPA1 (36% identical), CPA4 (35% identical), CPO (34% identical).